PHYHD1 (phytanoyl-CoA dioxygenase domain containing 1)
Description:
2-oxoglutarate(2OG)-dependent dioxygenase that catalyzes the conversion of 2-oxoglutarate to succinate and CO(2) in an iron-dependent manner. However, does not couple 2OG turnover to the hydroxylation of acyl-coenzyme A derivatives, implying that it is not directly involved in phytanoyl coenzyme-A metabolism. Does not show detectable activity towards fatty acid CoA thioesters. [Isoform 2]: Isoform 2 probably lacks enzyme activity. [Isoform 3]: Isoform 3 probably lacks enzyme activity.
Synonyms: MGC16638
Tractability: Small molecule: a structure with a bound ligand is known.
Gene: Protein-coding gene on chromosome 9 (128,920,966 to 128,942,042, forward strand). Ensembl gene ENSG00000175287.
Subcellular location (Human Protein Atlas): Nuclear speckles
Gene Ontology:
Molecular function: 2-oxoglutarate-dependent dioxygenase activity; protein binding
Genetic constraint (gnomAD): Loss-of-function variants: 42 observed, 44.93 expected, observed/expected ratio (o/e) 0.93, 90% interval 0.73 to 1.21. The upper end of that interval is the gene's LOEUF score, 1.21, which puts it in group 5 of 6, group 1 being the genes least tolerant of losing a copy. Missense variants: 342 observed, 382.88 expected, observed/expected ratio (o/e) 0.89, 90% interval 0.82 to 0.98. Synonymous variants: 139 observed, 149.83 expected, observed/expected ratio (o/e) 0.93, 90% interval 0.81 to 1.07.
Homologues: Orthologues: macaque PHYHD1 (95% identical), dog PHYHD1 (88% identical), mouse Phyhd1 (86% identical), rat Phyhd1 (84% identical), guinea pig PHYHD1 (81% identical), tropical clawed frog phyhd1 (67% identical), rabbit PHYHD1 (65% identical), zebrafish phyhd1 (65% identical), chimpanzee PHYHD1 (60% identical), pig PHYHD1 (57% identical), Caenorhabditis elegans Y105C5B.9 (46% identical), Drosophila melanogaster Phyhd1 (44% identical).
Diseases named in the same sentence as PHYHD1 in open-access papers:
PHYHD1 is named in the same sentence as 8 diseases in open-access papers, as found by Europe PMC text mining. Sharing a sentence is not in itself a finding about the gene and the disease. The quoted sentences say what the papers report.
pituitary adenoma (2 papers, 2021 to 2025). "For instance, one research had shown that the DNA methylation level of PHYHD1 was related to the invasion of non‐functioning pituitary adenoma." (PMID 34453418, 2021). "Additional genes—PHYHD1, LTBR, MYBPHL, C22orf42, PRR5, ANKDD1A, RAB13, CAMKV, KIFC3, WNT4, and STAT6—were implicated in the invasive behavior of non-functioning pituitary adenomas (NFPAs)." (PMID 39859246, 2025).
esophageal adenocarcinoma (1 paper, 2021). A malignant tumor with glandular differentiation arising predominantly from Barrett mucosa in the lower third of the esophagus. "The combination of SLC26A9 with AP002478.1, BHLHA15, FFAR2, IGFBP1, KCTD8, and PHYHD1 was also identified as a gene signature for personalized prognosis prediction and targeted therapy of esophageal adenocarcinoma." (PMID 35008199, 2021).
laryngeal squamous cell carcinoma (1 paper, 2021). A squamous cell carcinoma that arises from the larynx. "Reports of PHYHD1 in cancer are rare, and bioinformatics analyses have shown that PHYHD1 is associated with the prognosis of laryngeal squamous cell carcinoma." (PMID 34234806, 2021).
prostate carcinoma (1 paper, 2019). A carcinoma that arises from epithelial cells of the prostate gland. "PHYHD1 is recently identified as a predictor for progression-free survival and metastasis in prostate cancers." (PMID 31703592, 2019).
cancer (5 papers, 2020 to 2025). A tumor composed of atypical neoplastic, often pleomorphic cells that invade other tissues. "And many studies have shown that the high expression of PCGEM1 and PHYHD1 can promote the value-added migration and invasion of cancer, affecting prognosis." (PMID 36313300, 2022). "PHYHD1, though rarely studied in cancer, may be involved in lipid metabolism and redox balance." (PMID 40496864, 2025). "In addition to these widely studied proteins, there were still several proteins whose roles in cancer were unclear such as PLCX3, PHYHD1 and PLIN3, which provided a new direction for cancer research." (PMID 33200655, 2020). "Nevertheless, information regarding the role of PHYHD1 in cancer is lacking." (PMID 33005105, 2020).
tumor (5 papers, 2015 to 2026). "These analyses identified several differentially methylated genes linked to invasiveness (e.g., PHYHD1, WNT4, STAT6, CDH1, CDH13), aggressive behaviour (e.g., AIP, PDCD1, LINE-1), and tumour regrowth (e.g., TERT, FAM90A1, ING2)." (PMID 41866138, 2026). "In contrast, BTG2, MT1E, and PHYHD1 were identified as protective factors in our model, potentially functioning as suppressors of tumor progression." (PMID 40496864, 2025). "Moreover, the roles of other model genes such as CHORDC1 and PHYHD1 warrant further experimental exploration, particularly in the context of tumor metabolism and immune escape." (PMID 40496864, 2025). "The DNA methylation and expression levels of PHYHD1, LTBR, MYBPHL, C22orf42, PRR5, ANKDD1A, RAB13, CAMKV, KIFC3, WNT4 and STAT6 are associated with tumor invasion, and these genes may become the potential genes for targeted therapy." (PMID 31796052, 2019).
PHYHD1 also shares sentences with these, for which no sentence is quoted: carcinosarcoma (1 paper); neurological disease (1).